CCL3 (C-C motif chemokine ligand 3)
Diseases named in the same sentence as CCL3 in open-access papers (continued):
Sharing a sentence is not in itself a finding about the gene and the disease.
tumor (continued). "Nevertheless, CCL3 could potentially also have a positive role in facilitating antitumor immune responses by recruiting DCs to the tumor site, especially in combination with the pro-inflammatory environment commonly established with oncolytic viruses." (PMID 32355275, 2020). "We next established an in vivo model to investigate if CCL3/CCL4-secretion influences endogenous leukocyte recruitment to tumours engrafted in mice, and showed that CCL3/CCL4-secreting tumours consistently recruit more endogenous NK cells than contralateral control tumours." (PMID 33046212, 2020). "Both CCL3 and CCL4 cause the recruitment of MDSC into the tumor niche via CCR5." (PMID 33076281, 2020). "Previously, several evidence models suggested that fibroblast-derived CCL3 could activate tumor progression." (PMID 32349303, 2020). "In addition, the tumor-derived cytokines CXCL1, CCL3, CXCL2, TIMP-1, and TNF-α, which have been implicated in the generation, migration, and activation of MDSCs at the tumor site, were regulated by the modulation of MDSCs." (PMID 33091036, 2020). "Moreover, examination of cytokine/chemokine production in the tumor microenvironment revealed an increase in the levels of chemoattractive cytokines such as CCL3, CCL4, CCL5, CXCL9, CXCL10 and CXCL11." (PMID 32033490, 2020). "In addition, CCL2, CCL3, and CCL4 were reported as chemokines associated with worse prognosis and faster tumor progression." (PMID 33238581, 2020). "In addition, CCL3 and CCL4 cause the recruitment of CAF via CCR5, which is of great importance for the functioning of a tumor and the initial stages of metastatic niche formation in bones." (PMID 33076281, 2020). "It remains to be explored whether adoptive transfers using lower CTL numbers or earlier following tumour engraftment would result in a more dominant role for CCL3 and CCL4-mediated homotypic signalling in recruitment into solid tumours." (PMID 33046212, 2020). "We extended these observations to tumor biology where the muted responses toward CCL2 and CCL3 due to the loss of VISTA clearly predicted an alteration in the chemotaxis of monocytic cells to the tumor site and a change in the immune cell demography of the TME." (PMID 31803182, 2019). "Whether local CCL3 concentrations in the tumor microenvironment might impact the occurrence of thromboembolic events has not been investigated." (PMID 31847343, 2019). "Indeed, we and others have shown that in vitro tumor-conditioned tumor-associated macrophages (TAMs) exhibit a mixed M1/M2 macrophage phenotype, expressing both M2 (CD163 and CD206) and M1 (IL-1β, IL-6, TNF-α, and CCL3) markers." (PMID 30917934, 2019). "NK cells play a critical role in anti-tumor immunity and they could respond to several chemokine signals, including CCL3/CCL4/CCL5 via CCR5 and CXCL9/CXCL10 via CXCR340–42." (PMID 30718511, 2019). "In addition, NK cells can release pro-inflammatory cytokines and various chemotactic factors (IFNγ, TNFα, GM-CSF, CCL3/CCL4) potentially amplifying immune responses to the tumor." (PMID 30459756, 2018). "In attempt to dissect whether CCL3 influences the tumour milieu, we evaluated the expression of molecules involved in tumour proliferation (EGF, FGF, TGF-β and TNF-α) and angiogenesis (TGF-β1, VEGFa and VEGFb)." (PMID 28881626, 2017). "In both the in vitro tumor spheres and the in vivo murine model, there was a significant increase in the factors associated with M1 macrophage polarization, such as CCR5-binding chemokines (CCL3, CCL4, and CCL5), interleukins (IL-6 and IL-1β), and TNF-α." (PMID 28670313, 2017). "Again, the WT mice exhibited an increased tumour formation when compared with the CCL3-/- mice." (PMID 28881626, 2017). "The decreased expression of the adhesion molecules Itga4 and Vtn in the SCC lesions from the CCL3-/- mice may be indicative of the fact that CCL3 activate neoplastic cell adhesion and motility within the tumour microenvironment as described for other tumours." (PMID 28881626, 2017).
tumor (continued). "Extracellular matrix component degradation is an essential step in tumour invasion, and therefore, we analysed whether CCL3 induces the expression of matrix metalloproteinases (MMPs)." (PMID 28881626, 2017). "Therefore, we examine how CCL3 produced by L3TU influence cellular traffic to the TDLN during the early phase (≤10 days) of immune priming following tumor inoculation." (PMID 29109732, 2017). "CCL3 might stimulate cancer progression by promoting leukocyte accumulation, angiogenesis and tumour growth." (PMID 28881626, 2017). "We hypothesize that the continuous presence of autologous tumor-derived CCL3 (aCCL3) in the TME will lead to the generation of a greater antitumor cellular response in the TDLN." (PMID 29109732, 2017). "However, the crosstalk between chemokine (C-C motif) ligand 3 (CCL3), which facilitates tumor progression and metastasis." (PMID 26713602, 2016). "Upon tumour antigen pulsing, high levels of chemokines that sustain the recruitment of circulating DCs to inflamed tissues, such as CCL3, CCL4, were expressed, whereas at late time-points constitutive lymphoid chemokine such as CCL2, CCL8, CXCL10, CXCL12 and RANTES were selectively up-regulated." (PMID 26795765, 2016). "The results show that knockdown of CCL3 decrease 40% of hemoglobin concentration in tumor." (PMID 26713602, 2016). "Knockdown of CCL3 profoundly suppressed tumor growth in mice." (PMID 26713602, 2016). "Overall, these results suggest that CCL3 promotes angiogenesis and tumor growth in vivo." (PMID 26713602, 2016). "However, when we compared the expression of the chemokine genes in MM BM (5TGM1 tumor-bearing mice) versus tumor-free BM, we found that CCL3 and CCL2 expression was higher in MM BM (p < 0.01)." (PMID 26155942, 2015). "Thus, our data indicated that MOs were attracted to the MM tumor bed by chemokines CCL3, CCL14 or CCL2 because the process was significantly attenuated by antibodies directed against these chemokines." (PMID 26155942, 2015). "Finally, we performed non-parametric correlation (Spearman) analysis for CCL4 in the subcutaneous adipose tissue and for CCL3 in the tumor, having found a statistically significant positive correlation (p = 0.0448) only for the cachectic patients." (PMID 26732354, 2015). "CCL3 has been detected in infiltrating cells and tumor cells." (PMID 24047437, 2013). "Moreover, CCL3 preferentially recruits pre-DCs to tumor locations, as antibody mediated neutralization of CCL3 does not result in a decrease in any other CD45+ leukocyte subset, nor does it alter the frequency of splenic pre-DCs." (PMID 24339824, 2013). "In addition, CCL3 attracts macrophages to the tumour where they produce VEGF-A and other cytokines, thus circumventing the VEGF-A usurping." (PMID 23914254, 2013). "The increase in CCL3 (3.69 and 3.08, respectively) might indicate the presence of G4 tumor cells as CCL3 was one of the genes upregulated in G4 vs. G3 tumor cells." (PMID 23029164, 2012). "Our data indicate that both CCL3 and IL-6 are produced at high levels by tumor-associated DCs (not shown), which is supported by independent reports." (PMID 21113407, 2010). "In addition, they also indirectly shift the balance between tumor reactivity and tumor tolerance by recruiting through e.g. CCL3, CCL4, and CCL5 as well as be promoting the induction of T cell-suppressive Tregs through the release of IL-10 or TGF-β, among others." (PMID 40050933, 2025). "In addition, CCL3 has a role in the promotion of angiogenesis, which may increase the supply of oxygen and nutrients to tumors and promote tumor growth and metastasis." (PMID 41376630, 2025).
tumor (continued). "It has extensively been reported that these anti-tumour drugs impact the tumour microenvironment (TME), target human tumour-associated macrophages (hTAM), and inhibit the transcription of pro-inflammatory cytokines such as CCL2 (chemokine ligand 2), IL-6, VEGF, CCL3, CCL7, and CCL14." (PMID 38257245, 2024). "Therefore, whether CCL3 chemokine signaling promotes M1 polarization or M2 polarization in tumors needs to be judged according to tumor types and the characteristics of macrophages." (PMID 36173487, 2023). "Cxcl2, Ccl2, Ccl3, and Ccl8 can act as chemoattractants for myeloid cell recruitment in tumors, while Csf1, Csf2, and Csf3 are central to controlling the recruitment, proliferation, and differentiation of immunosuppressive myeloid cells, including macrophages and neutrophils in the tumor." (PMID 37138326, 2023). "Above all, CCL18/CCL3 blockade could elicit significant antitumor effects in ESCC through preventing the infiltration of tumor-associated macrophages and proliferation of ESCC cancer cells, which might be mediated by CCL3/CCR1, CCL3/CCR5 and CCL18/PITPNM3 pathways." (PMID 36850011, 2023). "Interestingly, OVs induce a strong antiviral tumor immune response through the production of cytokines like type-1 interferon that in turn promotes PD-L1 expression on tumor cells and also cytokines, such as CCL3 and CCL4, attracting PD-1+ or CTLA-4+ immune cells within TME." (PMID 35392236, 2022). "However, CCL3 was the only chemokine that upregulated the percentage of CD45+ cells out of total cells from the tumor, suggesting it might have a broad impact on a variety of leukocytes leading to an unbiased ratio of cDCs or T cells in CD45+ cells." (PMID 36654820, 2022). "Therefore, whether LCK may promote the formation of TLSs and increase the anti-tumour function of TLSs through N1-TAN induction of CCL3, CXCL9 and CXCL10 aggregation remains to be further investigated." (PMID 36291944, 2022). "For example, tumor-derived PAI-1 promotes the migration of monocytes and polarizes tumor-associated macrophages (TAMs) towards proinflammatory phenotypes, leading to the production of proinflammatory and angiogenesis-promoting factors such as IL-1, IL-8, CCL2, CCL3, CCL5, and VEGF." (PMID 34912726, 2021). "Pathogenic microorganisms and tumor cells can be eliminated by M1 macrophages by acute proinflammatory response, immune activation reaction, and cytophagy through the release of proinflammatory factors, such as NO, IL-1β, IL-6, TNF-α, and chemokines such as CCL2, CCL3, CCL5, CXCL9, and CXCL10." (PMID 34506209, 2021). "While CCL3 and IL10 (upregulated in FI-like tumors) have been described as molecules able to elicit antitumor response, the molecules upregulated in OSE-like tumors have all been associated with the induction of immunosuppressive response and increased tumor invasiveness." (PMID 33121525, 2020). "However, in a tumor both CCL3 and CCL4 may be cleaved by cathepsin D and chemokine decoy receptor ACKR2/D6, which suppresses the anti-cancer effect of these two CC chemokines." (PMID 33076281, 2020). "Inflammatory CC (CCL2, CCL3, CCL5) and CXC (CXCL1, CXCL2, CXCL5, CXCL6, and CXCL8) chemokines recruit at the tumor site CCR2+ monocytes and CXCR2+ neutrophils that differentiate into tumor associated macrophages (TAMs) and tumor associated neutrophils (TANs), exerting pro- or anti-tumoral role." (PMID 30894861, 2019). "Thus, increased IL-10 and decreased CCL3 production in ABC DLBCL that display augmented β-catenin activation may add to an immunosuppressive tumor microenvironment." (PMID 26776161, 2016). "Through mechanistic perturbations of neutrophil-derived CCL3 in mice, we show that it sustains TAN survival in hypoxic tumor regions via CCR1-dependent signaling." (PMID 41650972, 2026).
tumor (continued). "Accumulating evidence indicates that inflammatory mediators-including CCL2, CCL3, CCL5, CXCL1, CCL20, TNF-α, IL-6, IL-8, and TGF-β-contribute to tumor growth, metastasis, immune modulation, and therapeutic resistance." (PMID 42245673, 2026). "The upregulation of chemokine genes Ccl3, Ccl5, Cxcl9, and Cxcl10 suggests that these activated CD8+ T cells possess increased migratory capacity, allowing them to infiltrate the tumor microenvironment more effectively." (PMID 40534857, 2025). "Further analysis showed increased production of proinflammatory interleukins such as IL‐1β and IL‐16 and accumulation of various chemotactic agents, including CCL3, CCL4, CCL5, CXCL9, CXCL10, and CXCL11, in the tumor tissue." (PMID 41221154, 2025). "The number of NK cells in CRC is limited, even if the levels of intratumoral IFN-γ, CCL3, CXCL10 and CXCL12 contributing to the NK cells recruitment to the inflamed tumor area are elevated." (PMID 40136652, 2025). "In a mouse melanoma model, basophils released CCL3 and CCL4, which played a crucial role in attracting CD8+ T cells to the tumor site, thereby promoting tumor rejection." (PMID 40873585, 2025). "On the molecular level, TACC2 promoted the transcription of the chemokines CCL3 and CCL4 by preventing nuclear translocation and thereby facilitating CD8+ T-cell infiltration into the tumor microenvironment." (PMID 41153795, 2025). "Like CXCL10 and CXCL11, CCL3 and CCL4 have been attributed both tumor-promoting and anti-tumor effects." (PMID 40895532, 2025). "Consistent with the reduction of IL-1α, CCL2, and CCL3 in SHP2-silenced tumors, IHC revealed that tumor-infiltrating CD45+ hematopoietic cells and F4/80+ macrophages were significantly reduced in SHP2-silenced B16F10 tumors compared with controls." (PMID 40131370, 2025). "The expression of chemokines, such as CCL2, CCL3 and CCL5, in the tumor microenvironment in both human and murine models are associated with enhanced recruitment of myeloid-derived cells including macrophages." (PMID 39566333, 2025). "The expression pattern between the different groups seen in the expression of CCL3 was similar to that of DCN, with the addition of tumour tissue of the severely fibrotic patients being upregulated compared to the normal SI, albeit lacking significance." (PMID 40998421, 2025). "CCL3 plays an important role in recruitment of CD8+ T cells, NK cells and macrophages, particularly proinflammatory (M1) to the tumor microenvironment." (PMID 40484866, 2025). "Studies have also shown that intratumoral basophils enhance the infiltration of T cells by producing chemokines CCL3 and CCL8, confirming the important role of basophils in tumor rejection." (PMID 40131539, 2025). "Between ARGs_Low tumour cells and T cells, ITGB1-CD46 and ITGB1-ENG were ligand-receptor pairs with strong regulatory potential, while COL1A2, CCL3, SERPINE1, FN1 and CDKN1A were top genes target to TGFB1." (PMID 40830065, 2025). "At the molecular level, transcription factors such as STAT1, CEBPB, HIF1A, and REL, collectively drive MDSCs expansion, while chemokines like CCL3, CCL4, CCL8 and IL1B regulate their migration within the tumor microenvironment." (PMID 41252877, 2025). "On the one hand, they secrete the chemokines CCL3 and CXCL12, which recruit macrophages to the tumour site." (PMID 39827226, 2025). "NF-κB alters the tumor microenvironment by modulating the secretion of cytokines and chemokines (GDF15, CCL3, and CCL4), promoting tumor cell survival and drug resistance." (PMID 40760228, 2025). "These T cells also recruit antitumor macrophages to the tumor microenvironment via CCL5/4-CCR5 and CCL3/CCL3L3-CCR1 signaling interactions." (PMID 41203637, 2025). "Tumor microenvironment (TME) soluble mediator (Ccl2, Ccl3, Ccl4, Ccl5) and tumor cell marker (NeuN, Gpr17) RNA expression was quantitated by qRT-PCR." (PMID 41497446, 2025).
tumor (continued). "In the tumor microenvironment, chemokines such as CCL2, CCL3, CCL4, and CCL5 attract monocytes that differentiate into TAMs." (PMID 39941858, 2025). "In parallel, TNF-β and chemokines like CCL3 and CCL20 are critical for orchestrating immune cell recruitment and enhancing tumor surveillance." (PMID 40860824, 2025). "It is known that PBMC recruitment plays essential roles in tumor progression and metastasis and that cancer cells are able to recruit them by secreting several chemokines, such as CCL2, CCL3, CCL4, and CCL5 among many others." (PMID 40112045, 2025). "As such, interruption of these interdependent nodes resulted in inhibition of paracrine factors that attract T cells (Ccl2, Ccl3) and those important for TAM support of tumor growth (Ccl4, Ccl5)." (PMID 41497446, 2025). "Regarding sensory fibers, it has been observed that their stimulation by melanoma tumor cells induces the expression of proinflammatory cytokines, such as CCL2, CCL3, CCL5, which speed up MDSC recruitment and tumor growth." (PMID 41306965, 2025). "NK cells rarely infiltrate tumors because of immunosuppressive microenvironments, although high-density MCs can release cytokines, such as CXCL8, CCL3, IFN, and histamine, which can recruit NK cells to suppress tumor progression." (PMID 41425713, 2025). "The cluster 6 monocytes were defined by high expression of multiple pro-tumor genes (IL1B, SERPINB2, CCL2, CXCL1, CXCL5, CXCL8, CCL3, CCL20)." (PMID 40176808, 2025). "The tumour-biased CXCL8hi_IL1Bhi_Mac macrophages secreted proinflammatory and tumour-supporting cytokines like CXCL8, IL1B, and CCL3, inducing cancer cell growth, invasion, and metastasis." (PMID 41312167, 2025). "The expanded NK cells express the chemokine receptors CXCR3, CCR5, and CXCR6, and the lung of tumor-resected mice express mRNA of the corresponding ligands CXCL9/10/11, CCL3/4/5, and CXCL16." (PMID 39835538, 2025). "Inhibition of CCL3 signaling (via CCR5 blockade) led to significant decreases in TRAF6 and NF-κB activation and a corresponding drop in tumor cell proliferation." (PMID 41153795, 2025). "CCL3 and CCL4 can promote migration of immunosuppressive MDSC and TAMs into the tumor microenvironment (TME) and have been shown to correlate with worsening patient outcomes." (PMID 38108458, 2024). "As an adjuvant therapy, exogenous CCL3 not only augments recruitment and activity of CD8+ T cells within the TME but also promotes generation of tumor-specific T cell memory, thereby enhancing antitumor immunity." (PMID 38744851, 2024). "We identified pro-inflammatory cytokines (IL1A, IL1B, IL6), and chemokines (CCL3, CXCL2, CXCL3) that promote inflammation-promoted neoplasia." (PMID 38529274, 2024). "In the context of NPC, CCL3 or CCL4 can be expressed by malignant cells and tumor vascular endothelial cells." (PMID 39483474, 2024). "In tumors, they are classified into two phenotypes: an N1 neutrophil phenotype with anti-tumor activity, which induces direct or indirect cytotoxicity by producing TNF-α, CCL3 and expressing ICAM-1." (PMID 39179536, 2024). "Immunofluorescence staining in tumour-bearing liver from KPC mice and littermate controls confirmed that the CCR5 ligands CCL3, CCL4 and CCL5, and the cytokines IL-12, IL-15 and IL-18 were produced by KCs in peritumoural liver." (PMID 38326607, 2024). "In conclusion, the results of the current study confirmed that CCL3/VIRMA/SIRT1 pathway promotes ICC proliferation and tumor metastasis in vivo." (PMID 36691046, 2023). "The enhancement of IL-37 expression by HCC cells is accompanied by an increase in the levels of CCL3 (chemokine (C-C motif) ligand 3) and CCL20, which further promotes the recruitment of CD1a+ dendritic cells (DCs) in the tumor infiltrate." (PMID 37298214, 2023). "This decreasing trend was also observed for other chemoattractants important for recruiting immune cells to disrupt tumor growth, specifically MIG (CXCL9), MIP-1ɑ (CCL3), and MIP-1β (CCL4)." (PMID 36968140, 2023).